EXOC6 (exocyst complex component 6)
Description:
Component of the exocyst complex involved in the docking of exocytic vesicles with fusion sites on the plasma membrane. Together with RAB11A, RAB3IP, RAB8A, PARD3, PRKCI, ANXA2, CDC42 and DNMBP promotes transcytosis of PODXL to the apical membrane initiation sites (AMIS), apical surface formation and lumenogenesis (By similarity).
Synonyms: SEC15L; SEC15L1; FLJ1125; DKFZp761I2124; MGC33397; Sec15; EXOC6A; SEC15L3; Sec15p
Tractability: Antibody: its Gene Ontology location is reachable by antibodies, with high confidence. PROTAC: ubiquitination databases record sites on it; its protein half-life has been measured.
Gene: Protein-coding gene on chromosome 10 (92,826,831 to 93,059,493, forward strand). Ensembl gene ENSG00000138190.
Subcellular location: Cytoplasm; Cytoplasm, perinuclear region; Cell projection, growth cone; Midbody, Midbody ring
Subcellular location (Human Protein Atlas): Basal body; Centrosome; Cytosol
Pathways (Reactome):
Metabolism of proteins: Insulin processing
Organelle biogenesis and maintenance: VxPx cargo-targeting to cilium
Vesicle-mediated transport: Translocation of SLC2A4 (GLUT4) to the plasma membrane
Gene Ontology:
Molecular function: protein binding
Biological process: exocytosis; Golgi to plasma membrane transport; membrane fission; mitotic cytokinesis; intracellular protein transport
Cellular component: cytoplasm; cytosol; exocyst; plasma membrane; Flemming body; growth cone; perinuclear region of cytoplasm
Genetic constraint (gnomAD): Loss-of-function variants: 23 observed, 41.38 expected, observed/expected ratio (o/e) 0.56, 90% interval 0.4 to 0.79. The upper end of that interval is the gene's LOEUF score, 0.79, which puts it in group 3 of 6, group 1 being the genes least tolerant of losing a copy. Missense variants: 464 observed, 486.9 expected, observed/expected ratio (o/e) 0.95, 90% interval 0.88 to 1.03. Synonymous variants: 171 observed, 161.58 expected, observed/expected ratio (o/e) 1.06, 90% interval 0.93 to 1.2.
Homologues: Orthologues: dog EXOC6 (97% identical), pig EXOC6 (97% identical), rabbit EXOC6 (96% identical), guinea pig EXOC6 (96% identical), macaque EXOC6 (96% identical), mouse Exoc6 (91% identical), rat Exoc6 (91% identical), chimpanzee EXOC6 (90% identical), zebrafish exoc6 (85% identical), tropical clawed frog exoc6 (84% identical), Drosophila melanogaster Sec15 (41% identical), Caenorhabditis elegans sec-15 (39% identical). Paralogues in human: EXOC6B (71% identical).
Diseases named in the same sentence as EXOC6 in open-access papers:
EXOC6 is named in the same sentence as 23 diseases in open-access papers, as found by Europe PMC text mining. Sharing a sentence is not in itself a finding about the gene and the disease. The quoted sentences say what the papers report.
breast carcinoma (3 papers, 2021 to 2023). "Also, EXOC6 was found to be one out of five genes that was able to asses breast cancer risk with high accuracy." (PMID 34567063, 2021). "In the four-gene prognostic signature, EXOC6, GPC6, and NFATC2 were correlated with aggression of breast cancer." (PMID 35265226, 2022). "EXOC6 has been shown to be a predictor of breast cancer in previous study, but its role in GI cancers has not been reported." (PMID 37483484, 2023). "EXOC6 is reported to be an important respondent gene when the effects of a combination of the histone deacetylase inhibitor suberoylanilide hydroxamic acid (SAHA) and taxanes were tested for cytotoxicity using human breast cancer cell lines." (PMID 34567063, 2021). "While EXOC6 was observed to have distinct methylation profiles in brain tissues, it was not actively investigated in breast cancer Basal subtype samples in terms of multi-omics correlation." (PMID 34567063, 2021).
Type 2 Diabetes (2 papers, 2022 to 2023). "The exact role of EXOC6/6B in pancreatic β-cell function and risk of type 2 diabetes (T2D) required further investigations." (PMID 35336762, 2022). "EXOC6, encoding the exocyst complex component 6, is involved in translocation of the GLUT4 glucose transporter in adipocytes and insulin secretion in pancreatic β-cells, increasing the risk of type 2 diabetes." (PMID 37372445, 2023).
diabetes (1 paper, 2022). "Moreover, we investigated the impact of diabetes status on the EXOC6/6B expression using RNA-seq data." (PMID 35336762, 2022). "This study showed that EXOC6/6B are expressed in human pancreatic islets, but their expression was not influenced by diabetes or hyperglycemia status." (PMID 35336762, 2022). "Microarray and RNA-sequencing data were used to profile the expression of EXOC6/6b in human pancreatic islets with/without diabetes." (PMID 35336762, 2022).
Insulin resistance (1 paper, 2022). Increased resistance towards insulin, that is, diminished effectiveness of insulin in reducing blood glucose levels. "A possible explanation could be a compensatory response that regulates the expression of EXOC6/6B in β-cell or reflects that the diabetic donors suffer from insulin resistance rather than insulin secretion." (PMID 35336762, 2022).
insulinoma (1 paper, 2022). "In contrast to our data, it has been shown that overexpression of Exoc6 in mouse insulinoma βtc6 cells did not affect insulin secretion." (PMID 35336762, 2022).
myocardial infarction (1 paper, 2014). Gross necrosis of the myocardium, as a result of interruption of the blood supply to the area, as in coronary thrombosis. "Specifically, some shared PPIs such as APP - EXOC6 functions in the amyloid formation, which has been known to be involved in both stroke and myocardial infarction." (PMID 25539592, 2014).
cancer (3 papers, 2017 to 2023). A tumor composed of atypical neoplastic, often pleomorphic cells that invade other tissues. "Rab33b expression also correlates with Exoc6 expression, suggesting a relevance for the Rab33b-Exoc6 axis in cancer." (PMID 35521520, 2022). "The other three genes that showed consistent expression across all models, SORBS2, RGS12, and EXOC6, have been investigated as predictive or prognostic cancer biomarkers." (PMID 28798985, 2017). "Taken together, EXOC6/rs1339820 and ABCC11/rs75797074 showed some cross-cancer susceptibility in CG and CRC, and LRP5L maybe a potential susceptibility gene in GI cancers." (PMID 37483484, 2023). "Among which three genes, EXOC6 (Padj|ESCC=7.30×10-3, Padj|GC=6.00×10-4, Padj|CRC=2.6×10-2), LRP5L (Padj|ESCC=2.70×10-3, Padj|GC=5.70×10-3, Padj|CRC=1.65×10-2), MIR1263/LINC01324(Padj|ESCC=3.22×10-2, Padj|GC=4.36×10-2, Padj|CRC=3.26×10-2) were statistically significant in all three cancer types." (PMID 37483484, 2023). "Moreover, despite our analysis of The Cancer Genome Atlas (TCGA) datasets indicates a correlation between Rab33b and Exoc6 expression in cancer, the precise role of Rab33b-Exoc6 axis in cancer progression and metastasis has not been investigated and will require future studies." (PMID 35521520, 2022).
EXOC6 also shares sentences with these, for which no sentence is quoted: anemia (1 paper); atherosclerosis (1); autism (1); bacterial infection (1); Blindness (1); cardiovascular diseases (1); cyst (1); hearing loss (1); Hyperglycemia (1); Intellectual disability (1); iron deficiency (1); melanoma (1); narcolepsy (1); optic nerve hypoplasia (1); Stroke (1); tumor (1).